IL1B (interleukin 1 beta)
Diseases named in the same sentence as IL1B in open-access papers (continued):
Sharing a sentence is not in itself a finding about the gene and the disease.
pulmonary TB (26 papers, 2013 to 2025). "AIM2 detects intracellular DNA, facilitating the release of pro-inflammatory cytokines IL-18 and IL-1β, which have been associated with protection against pulmonary tuberculosis (PTB)." (PMID 38935691, 2024). "In summary, we demonstrate that TCA cycle remodeling is closely associated with IL-1β-mediated proinflammatory eicosanoid signaling in humans with pulmonary TB." (PMID 34559866, 2021). "The strong association between elevated succinate and IL-1β-mediated inflammatory signaling in our study suggests that TCA cycle remodeling plays a critical role in regulating the inflammatory response in humans with pulmonary TB." (PMID 34559866, 2021). "Changes in the serum levels of the proinflammatory cytokines TNF-α, IL-6, and IL-1β in the two groups of pulmonary tuberculosis patients before and after antituberculosis treatment were detected via ELISA." (PMID 40129950, 2025). "Serum levels of TNFa, IL1b, and TGFb1 were found to be related to radiological severity in patients with active pulmonary tuberculosis." (PMID 37834286, 2023). "It has been found that variants of IL1B were associated with latent tuberculosis infection, whereas variants of IL6 and TNFα variants were associated with pulmonary tuberculosis." (PMID 35153741, 2021). "It has been described that increased IL-1β levels directly correlate with X-ray severity in active pulmonary TB in humans, and increased lung pathology was also observed in our study over the course of infection." (PMID 29740435, 2018). "IL-32, a novel pleiotropic cytokine capable of inducing pro-inflammatory cytokines such as TNF-α and IL-1β and elevated in the sera of active pulmonary TB, can be triggered by IL-12." (PMID 27634911, 2016). "In this study, we enrolled a group of pulmonary TB patients in eastern China and observed more severity in iron-deficient patients whose MAIT, Vδ2+, and Treg cells showed lower frequency in the periphery while IL-1β and IL-7 were higher." (PMID 39898042, 2025). "Our findings are supported by independent human studies, which have consistently show elevated plasma concentrations of IL-1β in persons with pulmonary TB are correlated with markers of inflammation and associated with greater extent of disease and cavitation on chest radiograph." (PMID 34559866, 2021). "Also, antigen-specific IL-1b can be used as a biomarker for differential diagnosis of pulmonary TB and LTBI." (PMID 31781307, 2019). "Patients with pulmonary TB and bilateral or cavitary lesions of lung tissue had significantly higher levels of TNFa and IL1b compared with those with unilateral or non-cavitary lesions." (PMID 37834286, 2023). "To investigate whether this cytokine could play a similar role in human TB, we simultaneously measured the level of IL-1β and the number of neutrophils in broncheoalveolar lavage fluid (BALF) from patients with active pulmonary TB." (PMID 25329476, 2014). "In this Eastern-Romanian cohort, pulmonary tuberculosis exhibited a distinct hyper-TNF-α systemic profile that strongly correlated with early in-hospital mortality, while the levels of inflammatory cytokines such as IL-1β were significantly higher than in controls." (PMID 40806949, 2025). "Further,we analyzed the different genera present in pulmonary TB patients with and without injury at T2 and their correlations with the inflammatory factors TNF-α, IL-6, and IL-1β." (PMID 40129950, 2025). "For identification of adult pulmonary TB, regardless of HIV status, we identified an 8-marker signature consisting of FGF, IL-1β, IL-8, IL-10, IL-12p70, IL-13, MIP-1β and VEGF which gave an AUC of 0.78 (95% CI: 0.75, 0.84), sensitivity of 79% (95% CI: 75, 84) and specificity of 67% (95% CI: 60, 73)." (PMID 41164199, 2025).
rosacea (26 papers, 2016 to 2025). A chronic erythematous skin disorder that affects the face. "TNF-α, IL-6, IL-1α, and IL-1β are well-characterized inflammatory mediators in rosacea pathogenesis, driving key pathological processes including inflammatory cell infiltration, vascular hyperreactivity, and neuroimmune disorder." (PMID 40378103, 2025). "Specifically, the expression of two NF-κB target genes, namely IL-1α and IL-1β, was elevated in rosacea." (PMID 39351216, 2024). "A potential macrophage-targeted therapy for rosacea involves using inhibitors that target pro-inflammatory cytokine production, such as IL-1β, by macrophages." (PMID 37691916, 2023). "Studies have shown that macrophages in rosacea-affected skin express elevated levels of pro-inflammatory cytokines like IL-1β and TNF-α, surpassing those found in healthy skin." (PMID 37691916, 2023). "In this study, OPN was an inducer for the production of pro-inflammatory cytokine IL-1β in rosacea pathogenesis." (PMID 38250077, 2023). "Anakinra and canakinumab, IL-1β pathway inhibitors with a track record of reducing inflammation in other conditions, hold promise as potential treatments for rosacea." (PMID 37691916, 2023). "Due to its role in inflammation and angiogenesis, IL-1β is one of the most important pro-inflammatory cytokines in the pathogenesis of rosacea." (PMID 38250077, 2023). "Together, these findings demonstrated that iOPN promotes the progression of rosacea by regulating IL1B expression via ERK1/2 and JNK signaling pathways in keratinocytes." (PMID 38250077, 2023). "For example, skin samples from patients with rosacea exhibit increased gene expression for proinflammatory cytokines such as IL-8, IL-1β, and TNF-α." (PMID 27649161, 2016). "Furthermore, the involvement of sebaceous glands in rosacea is further supported by the identification of serum amyloid A (SAA) as a marker of activated sebocytes in rosacea skin samples, triggering IL-1β activation and secretion." (PMID 40422250, 2025). "These cells release molecules such as IL-1β, tumor necrosis factor, matrix metalloproteinases, reactive oxygen species, and the antimicrobial peptide cathelicidin, all contributing to inflammation in rosacea." (PMID 39859986, 2025). "Overexpression of TLR2 in rosacea patients may stimulate elevated production of pro-inflammatory cytokines, such as IL-8, IL-1β, and TNF-α, exacerbating the inflammatory response." (PMID 41009424, 2025). "Overall, increased expression of IL-1β may contribute to the aggravation of rosacea inflammation and blood vessel formation." (PMID 38250077, 2023). "Multiple studies suggested that IL-1β may be a major driver of rosacea for its increased expression." (PMID 38250077, 2023). "The expression of proinflammatory innate cytokines, including Th1 polarizing cytokines Il12b and Tnf; Th17/Th22 polarizing cytokines Il1b, Il23a, and Il6; and Il10 were significantly induced as compared with controls showing a similar expression profile as in rosacea." (PMID 36633910, 2023). "Moreover, studies demonstrated the potential relationship between MLT target genes (MMP9, CCND1, EGFR, ICAM1, PTGS2, and SERPINE1) and rosacea-related key genes (IL-6, IL-1β, IFNγ, IL-17, and TNF-α)." (PMID 34899707, 2021). "Activation of immune-mediated inflammatory pathways appears central to the pathogenesis of rosacea and involves the coordinated activity of several cell types, such as mast cells and macrophages, and the release of proinflammatory mediators, such as IL-6, IL-1β, and TNF-α." (PMID 39247187, 2024). "However, there was need to demonstrate the mechanism of elevated IL-1β in rosacea." (PMID 38250077, 2023). "In rosacea, activation of the MAPK signaling cascade drives inflammatory responses via regulation of IL-1β release." (PMID 40474977, 2025). "Meanwhile, RT-qPCR reflected that rosacea-related pro-inflammatory cytokines increased by LL37 were improved when epidermal TLR7 was silenced, for instance, Tnf-α, Il6 and Il-1β." (PMID 37780385, 2023).
rosacea (continued). "IL1B, IL6, NLRP3, and TNFa were important characteristic factors and critical mediators in the inflammation of rosacea." (PMID 38250077, 2023). "The pro-inflammatory cytokines including IL1B, NLRP3, and TNFa were also significantly upregulated in rosacea-like skin lesions of WT mice and remarkably downregulated in those of OPN KO mice." (PMID 38250077, 2023). "and pro-inflammatory cytokines (IL-8, IL-1β, TNF-α) in skin lesions implied that rosacea was not only a cutaneous inflammatory skin disorder but also with low-grade systemic inflammation." (PMID 36819686, 2023). "In LL37-induced rosacea-like mice, ART and its derivatives significantly inhibited the expression of pro-inflammatory factors (IL-1β, IL-6, and TNFα) and TLR2." (PMID 35950034, 2022). "Our study further verified that there is high macrophage infiltration into rosacea lesions, as well as enhanced expression of the inflammatory factors LL37, IL-1β, and SOCS3." (PMID 33545988, 2021). "Furthermore, gene expression analysis revealed elevated levels of inflammatory cytokines IL-13, IL-33, MCP-1, IL-1β, and TNF-α in LL-37-treated mice, consistent with rosacea’s symptoms and serum MCP-1 level." (PMID 41296102, 2025). "In patients with rosacea, the overexpression of TLR2 may stimulate elevated pro-inflammatory cytokine production (IL-8, IL-1β, and TNF-α, etc.), exacerbating the inflammatory response." (PMID 41009424, 2025). "Elevated levels of disease characteristic factors, such as KLK5, CAMP, TLR2, and proinflammatory cytokines (such as TNF‐α, IL1β, and IL6), and MMPs have been observed in the skin lesions of human rosacea patients as well as in a mouse model of rosacea induced by LL37." (PMID 39692542, 2024). "Interestingly, the rosacea patients who expressed higher OPN also expressed higher IL6, IL1B, NLRP3, and TNFa, suggesting that there was a correlation between the expression of OPN and pro-inflammatory factors in rosacea." (PMID 38250077, 2023). "Rosacea skin lesions exhibited more pronounced inflammatory cell infiltration than peripheral areas, with profound macrophage infiltration and inflammatory cytokines (TLR2, kallikrein 5, cathelicidin, TNF-α, and IL-1β)." (PMID 34322115, 2021). "Skin samples of patients with rosacea were subjected to histopathological (hematoxylin and eosin) and immunohistochemical (CD68, Toll-like receptor 2 (TLR2), kallikrein 5, cathelicidin, TNF-α, and IL-1β) evaluation." (PMID 34322115, 2021). "TNF-α and IL-1β are known to induce the expression of a subset of proinflammatory chemokines (CXCL1, CXCL8, CCL20, and CCL27) in keratinocytes, implying a potential pathway for TH1 and TH17 cell recruitment as well as neutrophil recruitment in rosacea lesional skin." (PMID 35832851, 2022). "Furthermore, IL-1β and TNF-α have an additional role as angiogenic factors VEGF; thus, these cytokines might explain the vascular hyper-reactivity seen in rosacea." (PMID 27649161, 2016). "Among innate cytokines, we observed a significant increase in TNF, IL1B, IL8, IL12B, IL23A, and IL10 — but not IL36B — in rosacea skin lesions as compared with skin from healthy donors." (PMID 36633910, 2023).
Seizure (26 papers, 2011 to 2025). A seizure is an intermittent abnormality of nervous system physiology characterized by a transient occurrence of signs and/or symptoms due to abnormal excessive or synchronous neuronal activity in the brain. "Research has shown that epileptic seizures are linked to heightened levels of PICs, primarily IL-1β, IL-6, and TNF-α." (PMID 38405667, 2024). "Seizures induced by focal application of kainate have been shown to cause microglial activation and an increase in interleukin-1β (IL-1β) production 24 h after kainate injection." (PMID 37047481, 2023). "Epileptic seizures are caused by IL-1β, a cytokine that promotes inflammation." (PMID 39598325, 2024). "The levels of TNF-α and IL-1β were significantly elevated in the PTZ-induced seizures model compared to the control group, which were reduced after the treatment of CA." (PMID 39901156, 2025). "In seizure models induced byPTZ, an increase in the levels of IL-1β, IL-6, and TNF-α cytokines in the hippocampus of rats has been reported." (PMID 40969414, 2025). "In rats with amygdala kindling SE, inhibition of the NLRP3 inflammasome downregulates the levels of IL-1β and IL-18, alleviates the severity of epileptic seizures, and decreases hippocampal neuronal apoptosis during the chronic epileptic phase." (PMID 38187384, 2023). "Clinical and basic studies have demonstrated that hyperactivation of IL-1β plays important role in the pathogenesis of febrile and epileptic seizures." (PMID 35707033, 2022). "Although a number of previous studies have shown that IL-1β contributes to epileptic seizures and can be considered as a therapeutic target for TLE, few of the studies have attempted to use specific neutralizing antibody in the treatment of TLE." (PMID 26925269, 2016). "During the acute course of SE or the chronic course of epileptic seizures, IL-1β is predominantly released by activated microglia or astrocytes, which may exacerbate the epileptic seizure and cause more serious consequences." (PMID 38187384, 2023). "Seizures can induce alterations in the expression of IL-1β and TNFα." (PMID 29867355, 2018). "In in vivo seizure models, astroglial cells are also key sources of anti-inflammatory molecules such as the IL-1 receptor antagonist (IL-1ra), an endogenous competitive IL-1 receptor blocker that controls IL-1β-mediated inflammation." (PMID 29867355, 2018). "Next, to further explore whether the inflammation was caused in PTZ-induced seizures model and examine the effects of CA on pro-inflammatory cytokines in PTZ-induced kindling model mice, western blotting was performed to examine the levels of TNF-α and IL-1β in the hippocampus of mice." (PMID 39901156, 2025). "In clinical studies, an increase in the content of proinflammatory cytokines IL-1β, interleukin-6 (IL-6), and tumor necrosis factor-α (TNF-α) was found in the cerebrospinal fluid of patients with epilepsy after an epileptic seizure." (PMID 37047481, 2023). "Seizure, neuronal apoptosis, oxidative stress (increased SOD and GSH-Px expression and decreased MDA and 8-OHdG expression) and inflammation (reduced IL-1β, TNF-α, and IL-6 expression) were reduced by miR-485 in epileptic cells." (PMID 34021541, 2021). "In this study, we found that IL-6 and TNF-α serum levels were significantly higher in FS patients than in febrile children without seizures, and IL-6 and TNF-α levels positively correlated with the serum levels of IL-1β in children with FS." (PMID 38218765, 2024). "Therefore, we infer that the anticonvulsive effect of UR, RP, and VA—at least for proinflammatory cytokines IL-1β, IL-6, and TNF-α—did not play a key role in the KA-induced acute seizure." (PMID 24381640, 2013). "Thus, in the current report we examined the effects of inhibiting microRNA‐155 (miR‐155) on the levels of IL‐1β, IL‐6 and TNF‐α, and expression of GAT‐1 and GAT‐3 in the parietal cortex, hippocampus and amygdala of rats with nonconvulsive seizure (NCS) following cerebral ischaemia." (PMID 31144434, 2019).
septic shock (26 papers, 2012 to 2024). Shock caused by infection; frequently caused by gram negative bacteria, although some cases have been caused by other bacteria, viruses, fungi, and protozoa; characterized by fever, chills, tachycardia, tachypnea, and hypotension. "These analyses revealed that patients suffering from septic shock have significantly higher systemic IL-8 or IL-1β plasma levels if they are infected with CovR/S+ or CovR/S− strains, respectively." (PMID 38408992, 2024). "Our previous works showed that ANI markedly reduced TNF-α and IL-1β levels in rats with LPS-induced septic shock." (PMID 38354108, 2024). "In septic shock patients, neutrophil counts, infection biomarkers (C-reactive protein, ferritin, and procalcitonin levels), and cytokines (IL-1β, IL-2R, IL-6, IL-8, IL-10, and TNF-α) increased significantly." (PMID 36845110, 2023). "BaP seems to dampen acute proinflammatory responses by suppressing proinflammatory cytokines (e.g., IL-1β) but induce anti-inflammatory cytokines (e.g., IL-10), and thus prevent septic shock." (PMID 37287978, 2023). "In a mouse model of LPS-induced septic shock, IL-1β levels in peritoneal lavage fluid and serum were measured by ELISA." (PMID 37400760, 2023). "IL‐1β and TNF reduced cardiomyocyte function in vitro, when cardiomyocytes were incubated with serum from septic shock patients, and IL‐1β immunoabsorption diminished the cardiodepressant activity of this serum." (PMID 34472725, 2021). "Likewise, the haemodynamic and metabolic manifestations of septic shock were attenuated by an IL‐1β antagonist." (PMID 34472725, 2021). "This tmTNF-α antibody significantly inhibited LPS-induced secretion of interleukin (IL)-1β, IL-6, interferon-β, and nitric oxide by monocytes/macrophages, and protected mice from septic shock induced by lipopolysaccharide (LPS) or cecal ligation and puncture, while reducing the bacterial load." (PMID 31383857, 2019). "IL-1β is another cytokine that mediates pro-inflammatory states but also plays an immunomodulatory role, so the hypomethylation of its gene may increase protein expression in septic shock patients, as we have previously demonstrated." (PMID 38235139, 2023). "In the LPS-induced murine septic shock model used in this study, the levels of IL-6, TNFα, MCP-1, and IL-10 increased 36 h after LPS administration, except IL-1β." (PMID 34066510, 2021). "Other factors including septic shock, ARDS, day 1 levels of IL-1β, IL-6, IL-8 and CRP, and day 1 SOFA and APACHE II scores, were also predictive of 60-day mortality." (PMID 28542440, 2017). "The results indicated that, similar to the effect of MCC950, treatment with carnosol downregulated IL-1β and TNF-α in the LPS-mediated septic shock mouse model in a dose-dependent manner, along with a reduction in the number of peritoneal exudate cells and peritoneal macrophages." (PMID 32312957, 2020). "Our results revealed that the antibody induced LPS resistance of monocytes/macrophages in vitro, showing downregulated LPS-induced production of NO, IL-1β, IL-6 and IFN-β, and conferred protection against LPS and CLP-induced septic shock, manifested as reduced inflammation and increased survival." (PMID 31383857, 2019). "Finally, TPO may depress cardiac contractility in septic shock, since it inhibits adrenergic receptor signal transduction in myocardiocytes, and cooperates with TNF-α and IL-1β to the cardio-depressant activity exerted in vitro by serum of septic shock patients." (PMID 26963510, 2016). "However, in septic shock patients, the correlation between IFNγ and IL-12 (p70) with CETPI, IL-1β, TNF-α, IL-6, IL-8, and IL-10, were not significant." (PMID 36536294, 2022).